VHL (von Hippel-Lindau tumor suppressor)
Diseases named in the same sentence as VHL in open-access papers (continued):
Sharing a sentence is not in itself a finding about the gene and the disease.
hemangioblastoma (continued). "Altogether, we can conclude that propranolol decreases the viability of tumor cells (HeLa and VHL-derived hemangioblastoma cells) by stopping proliferation and inducing cell death by apoptosis." (PMID 26394686, 2015). "In contrast, inactivation of VHL has been previously observed in only a minority of sporadic hemangioblastomas, suggesting an alternative genetic etiology." (PMID 25589003, 2014). "This is likely a consequence of lower VHL mutant allele fractions confined to the neoplastic “stromal” cells in sporadic hemangioblastomas, as compared to familial tumors that are characterized by heterozygous germline VHL alterations." (PMID 25589003, 2014). "Our findings support the central role of VHL inactivation in the molecular pathogenesis of both familial and sporadic hemangioblastomas." (PMID 25589003, 2014). "In summary, we find that inactivation of VHL is highly recurrent and characteristic of the majority of sporadic hemangioblastomas." (PMID 25589003, 2014). "Because of complexities of VHL, a better understanding of the pathological and clinical features of hemangioblastoma in VHL is essential for its proper management." (PMID 28326249, 2014). "The central role of VHL in the formation of sporadic hemangioblastomas suggests that the approach to these tumors can be universally considered as a single entity together with familial cases, which arise as a result of VHL disease." (PMID 25589003, 2014). "Application of these techniques to hemangioblastomas can comprehensively examine the role of VHL across the spectrum of this disease." (PMID 25589003, 2014). "Inactivation of the VHL tumor suppressor gene is responsible for both the hereditary tumors in VHL disease as well as sporadic renal carcinomas and hemangioblastomas." (PMID 19602254, 2009). "Another study on CNS hemangioblastomas found no hypermethylation of the VHL wild-type allele promoter." (PMID 40558831, 2025). "A study of 21 peripheral hemangioblastomas, 10 of which were confirmed or suspected to be VHL associated, found one negative case." (PMID 41302074, 2025). "Most VHL-associated hemangioblastoma present as solid, non-necrotic nodules, either solitary or accompanied by cysts." (PMID 40927231, 2025). "Finally, the same results were reproduced by a comparative study analyzing 11 VHL-related and 21 sporadic hemangioblastomas, where hypermethylation was detected only in sporadic cases." (PMID 40558831, 2025). "Recent publications suggest that a new drug, belzutifan, a hypoxia-inducible factor 2-alpha inhibitor shows promise as a therapeutic option for VHL-associated hemangioblastomas, particularly for patients not immediately requiring surgery (reviewed in 32–34)." (PMID 41024941, 2025). "Thus, two families were described in which children had hemangioblastomas, CCRC and/or pancreatic cysts, and germline VHL mutations." (PMID 40141393, 2025). "First, the NCDB lacks genetic and molecular data, most notably the absence of VHL mutation status, which limits differentiation between sporadic and VHL-associated hemangioblastomas." (PMID 40841556, 2025). "A diagnosis can be established if a patient carries a clinically actionable VHL variant with at least 1 VHL-related manifestation or has at least 2 VHL manifestations (1 being a hemangioblastoma) even in the absence of a genetic variant." (PMID 39950840, 2025). "Some hemangioblastomas were discovered by screening the family members of VHL patients." (PMID 39045559, 2024). "Clinically relevant mutations in Von Hippau Lindau (VHL) affect protein expression and degradation where patients with or without a mass lesion (i.e., hemangioblastoma) develop HC." (PMID 38439105, 2024). "The presence of embryonic hemangioblast proteins (Brachyury and TAL1) has not yet been investigated in VHL-associated tumors other than hemangioblastomas." (PMID 37174017, 2023).
hemangioblastoma (continued). "Interestingly, this manuscript is the first that describes both nuclear and cytoplasmic Brachyury expression in VHL hemangioblastoma tumor cells." (PMID 37174017, 2023). "Interestingly, DASEs already exhibit loss of VHL-heterozygosity (in contrast to normal surrounding tissue), and some have the ability to transform into frank VHL hemangioblastomas with mesenchymal components." (PMID 37174017, 2023). "Cell culture experiments could show that propranolol induced apoptosis in hemangioblastoma cells from VHL patients by downregulating HIF-dependent transcription." (PMID 36902129, 2023). "The analysis of sporadic RCC and VHL-associated hemangioblastoma archival tissues was subsequently conducted in an effort to evaluate the differential response observed between RCC and CNS hemangioblastoma lesions exposed to sunitinib in VHL disease." (PMID 36358730, 2022). "This age-related decline in proteasome function may partially account for the difference in the onset age of supratentorial hemangioblastoma between the VHL and the sporadic patient cases." (PMID 36760665, 2022). "Hemangioblastomas are formed by “stromal” cells (with VHL mutation) and rich blood vessels (without VHL mutation)." (PMID 34574050, 2021). "The mTOR pathway is a potential target for VHL‐related hemangioblastomas." (PMID 31317677, 2019). "Furthermore, the systemic therapy used for VHL Hemangioblastomas in CNS has been unsuccessful so far." (PMID 31296894, 2019). "In this family, the missense mutation on exon 1 of VHL resulted in a p.Gly104Val substitution which has not been described so far in the literature as being causative of PGL or hemangioblastoma." (PMID 29789510, 2018). "This combination could be potentially of high interest for both VHL related and sporadic patients with hemangioblastoma." (PMID 26920352, 2016). "For VHL-related hemangioblastoma, targeted therapy against CXCR4 and VEGFA could potentially be combined with conventional therapy as VHL-related disease is multiple and lesions often reoccur after surgery." (PMID 26920352, 2016). "Earlier studies in VHL related hemangioblastoma found upregulated CXCR4, CXCL12, and VEGFA." (PMID 26920352, 2016). "Tissue microdissection has showed VHL gene deletion in the stromal cells of hemangioblastomas, indicating that stromal cells are the true tumor cells derived from embryologically arrested hemangioblasts that are able to develop into hematopoietic and endothelial progenies under suitable conditions." (PMID 26394686, 2015). "One patient with a VHL mutation and a family history of clear-cell renal tumor and multiple hemangioblastomas had a PA presenting at 15 years (no typical VHL manifestations at this stage)." (PMID 25494863, 2015). "Biallelic VHL inactivation in hemangioblastoma results in insufficient degradation of HIF-1α, which then results in the inappropriate transcription of effectors normally expressed in hypoxic states, such as vascular endothelial growth factor (VEGF) or platelet derived growth factor B (PDGF B)." (PMID 25589003, 2014). "WES of germline DNA from the discovery cohort did not reveal any VHL mutations, indicating that these patients do not have VHL disease and that the tumors we evaluated are bona fide sporadic hemangioblastomas." (PMID 25589003, 2014). "The first explanation is that sporadic cases of hemangioblastoma may develop via alterations in genes involved in hypoxia-sensing pathways other than VHL itself that also result in a histologically-identical phenotype of exuberant angiogenesis." (PMID 25589003, 2014). "VHL genetic screening should be performed in cases of hemangioblastoma." (PMID 23781388, 2013). "In contrast, central nervous system (CNS)hemangioblastomas (HBs) (90.47% vs. 53.12%; p = 0.004),pancreatic cysts (76.19% vs. 28.12%; p = 0.001) and RCCs(57.14% vs. 12.5; p = 0.001) were more common in patientswith non-missense VHL variants." (PMID 39945572, 2025).
hemangioblastoma (continued). "Although our current study did not evaluate treatment response, the presence of FSHR1 in VHL-associated hemangioblastoma and other VHL-associated tumors could similarly reflect a vascular phenotype amenable to target inhibition." (PMID 41024941, 2025). "This study seeks to enhance our understanding of the growth dynamics of VHL-related hemangioblastomas, with a particular focus on determining the effect of dual HIF-α isoform inhibition on tumor progression, which could potentially contribute to the development of novel pharmacological strategies." (PMID 40427061, 2025). "Additionally, our results emphasize evaluating all hemangioblastoma patients for VHL, not limited by age, to identify genetic predispositions." (PMID 39950840, 2025). "In addition, the VHL genes of patients with hemangioblastoma were analyzed." (PMID 39850947, 2024). "Hence, propranolol could be a therapeutic tool to control hemangioblastoma growth in patients with VHL." (PMID 36902129, 2023). "However, a national study in Denmark found no disease-causing VHL variant in 21% (15/71) assumed VHL patients that underwent genetic testing, which included patients with a hemangioblastoma of the CNS10." (PMID 35304467, 2022). "Overexpression EGFR and TGFα may contribute to tumor growth in VHL-related hemangioblastomas." (PMID 32432044, 2020). "However, at present, the role of EGFR and TGFα in VHL-associated hemangioblastomas has not been examined." (PMID 32432044, 2020). "Regardless of tumor growth, VHL-associated hemangioblastomas may be resected to provide a surgical cure, while maintaining a low morbidity and excellent prognosis." (PMID 30345209, 2018). "Therefore, the aim of this study was to investigate CXCR4, CXCL12, and VEGFA protein expression in VHL-related and sporadic hemangioblastomas and to correlate this to size as measured by MRI before surgery to investigate possible differences between VHL-related and sporadic hemangioblastoma." (PMID 26920352, 2016). "Of note, while the validation specimens were selected as representing sporadic hemangioblastomas by clinical information and germline testing for most, it is possible that up to 10% of these patients without matched blood may have germline VHL mutations." (PMID 25589003, 2014). "To date, numerous pancreatic lesions have been reported in patients with VHL, including serous cyst neoplasia (SCN), pancreatic-neuroendocrine tumor (p-NET), adenocarcinomas, hemangioblastomas, metastasis of renal cell carcinoma and MSNN." (PMID 40918781, 2025). "We aimed to determine in VHL-related and sporadic hemangioblastomas CXCR4, CXCL12, and VEGFA protein expression and to correlate this to hemangioblastoma size and expression in normal surrounding tissue." (PMID 26920352, 2016). "High levels of VEGF are believed to contribute to hemangioblastoma formation; in animal models where VEGF is overexpressed or where VHL is inactive, visceral lesions resembling hemangioblastomas form." (PMID 25885645, 2015). "It was shown that the cell’s typical proteins Brachyury and TAL1 are expressed by a broader spectrum of VHL tumors rather than by hemangioblastomas only." (PMID 37174017, 2023). "This profile is consistent with sporadic tumors, e.g., hemangioblastomas, that inactivating mutations in the VHL gene is implicated with or without LOH of the VHL gene." (PMID 35774415, 2022). "Sporadic and VHL-related hemangioblastomas had the same level of CXCL12 expression, with strong expression in 75 % (12 out of 16) of sporadic hemangioblastomas and in 81 % (13 out of 16) of VHL-related hemangioblastoma cells." (PMID 26920352, 2016). "Moreover, we observed overall LTC rates of 91% and 85% in VHL and sporadic hemangioblastomas, respectively, but the difference was not significant." (PMID 40091097, 2025).
hemangioblastoma (continued). "In the same line, molecular analysis of the VHL gene from 57 surgically removed CNS capillary hemangioblastomas yielded no hypermethylation of the promoter due to the insufficient sample size (only two patients with VHL disease) and failure of amplification of the promoter fragment." (PMID 40558831, 2025). "In addition, our recent research suggests that the VHL-JAK-STAT pathway serves as an alternative signaling pathway that influences cell proliferation, maintenance of stem cell characteristics, and angiogenesis in hemangioblastoma." (PMID 39850947, 2024). "Also, an optic nerve tumor in a known VHL patient, is very likely to be a hemangioblastoma and not another rare optic nerve tumor." (PMID 39045559, 2024). "One patient had known VHL disease confirmed by sequencing (VHL exon 2 heterozygous deletion identified) with multiple small nodular cerebellar lesions on imaging suggestive of hemangioblastomas (biopsy not performed)." (PMID 30340515, 2018). "Mutations in the VHL gene inactivate the VHL protein and induces excessive vascular endothelial growth factor (VEGF), which promotes blood vessels to proliferate and to form retina hemangioblastomas in nonhypoxic conditions." (PMID 30477447, 2018). "However, unlike in familial VHL disease, prior studies have indicated that the majority of sporadic hemangioblastomas do not have identifiable germline or somatic alterations in VHL." (PMID 25589003, 2014). "An example is a report of a 38-year-old man who was diagnosed with cerebellar and spinal hemangioblastomas, CRCC, and polycystic pancreatic disease; however, NGS of a multigene panel using a standard pipeline for germline variants showed the absence of the VHL mutations on two occasions." (PMID 40141393, 2025). "Moreover, some mutations (VHL, NF1, and RET) are associated to other tumors rather than PGL (for instance, RET is associated to multiple endocrine neoplasia, VHL to hemangioblastomas, etc.), while other mutations are associated with metastatic forms of PGL (SDHB, FH, and SLC25A11)." (PMID 35054115, 2022). "An example is hemangioblastoma; 75% of these tumors are reportedly sporadic with or without LOH in the VHL gene." (PMID 35774415, 2022).
breast carcinoma (69 papers, 2004 to 2025). "The impetus for her testing was her extensive maternal and paternal family history of early onset breast cancer and the previous discovery of the same VHL pathogenic variant in her sister." (PMID 40063608, 2025). "While VHL mutations are rare in breast cancer, their protein levels are lower than those in normal breast cells." (PMID 38914543, 2024). "Breast cancer cells display relatively lower VHL protein levels as compared to normal breast cells, although mutations of VHL are rare in breast cancer." (PMID 38914543, 2024). "Although previous reports showed that mutations in VHL are quite rare in lung cancer and hepatocellular carcinoma, the status and function of VHL in breast cancer is much less studied." (PMID 36813923, 2023). "In breast cancer, oncogenic miR-429 was able to regulate hypoxia inducible factor-1α (HIF1α) pathway by directly targeting von-Hippel Lindau (VHL) mRNA, which caused increased proliferation and migration of breast cancer cells." (PMID 35004274, 2021). "We infected U2OS osteosarcoma, MDA-MB-468 mammary gland adenocarcinoma, A549 pulmonary adenocarcinoma and MDA-MB-231 breast cancer cells with retroviruses encoding the expression of VHL, aNSa1, VHL-aNSa1, aCS3 or VHL-aCS3, and monitored the endogenous SHP2 levels." (PMID 28490657, 2017). "Finally, our results confirmed that reduced Dicer expression was associated with poor survival in VHL-deficient ccRCC patients, consistent with the prognosis associated with reduced Dicer expression in lung, ovarian, and breast cancer patients." (PMID 26943772, 2016). "CBD has been shown to suppress angiogenesis and diminish the metastatic properties of breast cancer cells via the Src/VHL/HIF-1alpha signaling pathway (Sarcoma, Hypoxia-inducible factor 1-alpha, Von Hippel-Lindau Tumor Suppressor)." (PMID 40599866, 2025). "CAIX is regulated by the Von Hippel Lindau (VHL) protein (pVHL) and serves as a hallmark for multiple solid tumors, including RCC, HNSCC, glioblastoma, breast cancer, mesothelioma, and bladder cancer." (PMID 38491381, 2024). "The E3 ligase Von Hippel-Lindau (VHL) is an important tumor suppressor that is dysfunctional in multiple cancers, including breast cancer." (PMID 38914543, 2024). "To further illustrate that VHL hinders the oncogenic potential of breast cancer cells through its regulation of UBE3B, we depleted UBE3B in MDA-MB-231 and T47D cells following VHL ablation (referred to as VHL-KD#1+UBE3B-KD)." (PMID 38914543, 2024). "Collectively, VHL suppresses breast cancer cell proliferation, survival, and invasion, at least partially, by inhibiting UBE3B." (PMID 38914543, 2024). "Next, we assessed the effect of VHL on the UBE3B-HIF-2α axis-mediated breast cancer cell proliferation, survival, and invasion." (PMID 38914543, 2024). "Collectively, these findings demonstrate that K286 and K427 are key sites for VHL-mediated UBE3B ubiquitination in breast cancer cells." (PMID 38914543, 2024). "To further precisely outline the expression patterns of UBE3B and VHL in breast cancer cells, we performed immunostaining in breast cancer tissues." (PMID 38914543, 2024). "We analyzed VHL alterations in breast cancers collected in cBioPortal for Cancer Genomics databases and found that VHL gene is largely wild-type in breast cancer." (PMID 36813923, 2023). "Although mutations in VHL are frequently detected in VHL disease and ccRCC, the status of VHL in breast cancer remains poorly defined." (PMID 36813923, 2023). "On the other hand, VHL has been reported to be included in a robust predictive signature for patients with breast cancer." (PMID 36036061, 2023). "XZ9002, the first HDAC3-specific PROTAC, effectively reduces HDAC3 in breast cancer cells and is formed by the linkage of VHL E3 ligase and an inhibitor of HDAC3." (PMID 36770884, 2023). "Here, we report breast cancer cell-secreted exosomal miR-204-5p induces hypoxia-inducible factor 1A (HIF1A) in WAT by targeting von Hippel-Lindau (VHL) gene." (PMID 37620316, 2023).